ZNF121 (zinc finger protein 121)
Description:
May be involved in transcriptional regulation.
Synonyms: ZNF20; ZHC32; D19S204
Tractability: PROTAC: ubiquitination databases record sites on it.
Gene: Protein-coding gene on chromosome 19 (9,560,329 to 9,584,504, reverse strand). Ensembl gene ENSG00000197961.
Subcellular location: Nucleus
Subcellular location (Human Protein Atlas): Centrosome; Nucleoplasm; Nucleoli
Gene Ontology:
Molecular function: protein binding; DNA-binding transcription factor activity, RNA polymerase II-specific; RNA polymerase II cis-regulatory region sequence-specific DNA binding
Biological process: regulation of transcription by RNA polymerase II
Cellular component: nucleus
Genetic constraint (gnomAD): Loss-of-function variants: 2 observed, 2.08 expected, observed/expected ratio (o/e) 0.96, 90% interval 0.35 to 1.87. That is too few expected variants to judge how well the gene tolerates losing a copy. Missense variants: 368 observed, 488.44 expected, observed/expected ratio (o/e) 0.75, 90% interval 0.69 to 0.82. Synonymous variants: 171 observed, 167.28 expected, observed/expected ratio (o/e) 1.02, 90% interval 0.9 to 1.16.
Homologues: Orthologues: chimpanzee ZNF121 (99% identical), macaque ZNF121 (99% identical), mouse Zfp560 (54% identical), rat Zfp560 (52% identical). Paralogues in human: ZNF708 (49% identical), ZNF724 (49% identical), ZNF546 (49% identical), ZNF678 (48% identical), ZNF726 (48% identical), ZNF568 (48% identical), ZNF311 (48% identical), ZNF595 (48% identical), ZNF7 (48% identical), ZNF16 (47% identical), ZNF28 (47% identical), ZNF699 (47% identical), and 164 more.
Diseases named in the same sentence as ZNF121 in open-access papers:
ZNF121 is named in the same sentence as 9 diseases in open-access papers, as found by Europe PMC text mining. Sharing a sentence is not in itself a finding about the gene and the disease. The quoted sentences say what the papers report.
breast carcinoma (5 papers, 2018 to 2025). "In breast cancer samples B7 and B13, we detected in concordance with the ATAC-seq data increased accessibility for GRHL2, FOXA1, and ZNF121, a zinc finger protein, which was recently implicated in regulation of cell proliferation and breast cancer development." (PMID 31604930, 2019). "Among other things, suppression of the ZNF121 gene reduced the rate of proliferation in breast cancer cells." (PMID 34440124, 2021). "The novel zinc finger protein 121 (ZNF121) has been demonstrated to physically and functionally associate with the MYC oncoprotein to regulate cell proliferation and likely breast cancer development." (PMID 30524945, 2018). "Indeed, transient knockdown of ZNF121 significantly promoted the expression of ANG in both the T‐47D breast cancer cell line and the MCF10A non‐neoplastic human breast epithelial cell line." (PMID 30524945, 2018). "The ZNF121 mRNA level is also higher in breast cancer samples compared to normal tissues." (PMID 30524945, 2018). "ZNF121 has been shown to be a c-MYC-interacting protein with functional effects on MYC and cell proliferation in breast cancer." (PMID 40241172, 2025). "In lung and breast cancer cells, a correlation was shown between the expression of the ZNF121 and MYC genes: during the siRNA-mediated knockdown of ZNF121, MYC expression decreased and, accordingly, when ZNF121 was overexpressed, MYC expression increased." (PMID 34440124, 2021). "In addition, ZNF121 and MYC regulate each other's protein expression or stability, and ZNF121 indeed regulates cell proliferation, apoptosis, and likely breast cancer development." (PMID 30524945, 2018).
lung carcinoma (3 papers, 2019 to 2021). "In lung cancer, circular RNA hsa_circRNA_103809 acts as an oncogene through miR-4302/ZNF121/MYC axis." (PMID 31703640, 2019). "Hsa_circRNA_103809 promoted lung cancer cell proliferation and invasion by promoting ZNF121 expression via miR-4302 sponging, and thus elevated ZNF121 expression levels, subsequently increasing MYC levels in lung cancer." (PMID 34295810, 2021). "Besides, Liu’s research demonstrated that circRNA_103809 could upregulate ZNF121-dependent MYC expression via sponging miR-4302, and finally promote cell proliferation and metastasis in lung cancer." (PMID 32499818, 2020).
bladder cancer (1 paper, 2023). "CDK4, KPNA2, PFDN5, HSP90B1, and ZNF121 were identified as prognostic differential genes in bladder cancer." (PMID 37433010, 2023).
colon cancer (1 paper, 2021). "Therefore, we speculated that ZNF121 and HMBOX1 played a collaborative role with ZNF460 in carcinogenesis of colon cancer." (PMID 33976729, 2021).
intervertebral disc degeneration (1 paper, 2025). "ZNF121 influenced the development of intervertebral discs, and is responsible for intervertebral disc degeneration." (PMID 40965274, 2025).
tumor (5 papers, 2018 to 2025). "PAX5 transcripts are present at very low levels in normal tissue and are further reduced in tumours, whereas SALL4, ZNF770 and ZNF121 transcripts are upregulated in primary and metastatic tumours compared to normal colon." (PMID 40241172, 2025).
cancer (2 papers, 2021 to 2025). A tumor composed of atypical neoplastic, often pleomorphic cells that invade other tissues. "Future functional analyses will reveal whether ZNF770 and ZNF121 have binding affinities for 5hmC or 5mC and whether they interact with TET enzymes to regulate 5hmC accumulation in normal tissue or cancers." (PMID 40241172, 2025).
ZNF121 also shares sentences with these, for which no sentence is quoted: gastric cancer (1 paper); Sepsis (1).